CGAS (cyclic GMP-AMP synthase)
Diseases named in the same sentence as CGAS in open-access papers (continued):
Sharing a sentence is not in itself a finding about the gene and the disease.
infection (continued). "cGas KO mice were also more infected, also to about 5-fold-higher levels than wild-type mice, and the level of infection was the same as that of the CD11cCre-DDX41 mice." (PMID 29871919, 2018). "In the late phase of infection, cGAS is deSUMOylated by SENP2 and subsequently degraded via proteasome." (PMID 29546673, 2018). "The CD11cCre-DDX41 and cGas KO mice showed significantly higher levels of infection than the wild-type mice, while Stinggt/gt mice had the highest level of infection." (PMID 29871919, 2018). "Recent studies have shown that production of type I IFNs during infections with several bacterial pathogens requires both, cGAS and STING." (PMID 29298342, 2018). "Cyclic GMP-AMP synthase is essential for innate immunity against infection and cellular damage, serving as a sensor of DNA from pathogens or mislocalized self-DNA." (PMID 28963528, 2017). "Given that cGAS plays a role in the antiviral response to PDK53 infection, we next sought to determine how an RNA virus activates a cytoplasmic DNA sensor." (PMID 28620207, 2017). "Using a dengue virus serotype 2 (DENV-2) vaccine strain (PDK53), we show that infection creates an endogenous source of cytosolic DNA in infected cells through the release of mitochondrial DNA (mtDNA) to drive the production of cGAMP by cGAS." (PMID 28620207, 2017). "Many human cells can sense the presence of exogenous DNA during infection though the cytosolic DNA receptor cyclic GMP-AMP synthase (cGAS), which produces the second messenger cyclic GMP-AMP (cGAMP)." (PMID 28194029, 2017). "It is accepted that signaling through cGAS during the initial stages of infection is accompanied by the downstream activation of STING where it plays an essential role in type I interferon-dependant innate immunity in response to intracellular DNA." (PMID 28580319, 2017). "During an infection, DNA of microbial origin by binding to cGAS activates the cGAS/stimulator of interferon gene (STING) pathway thus triggering expression of inflammatory genes." (PMID 29445253, 2017). "Here, we decipher the distinct functions of two viral DNA sensors, IFI16 and cGAS, during active immune signaling upon infection with two herpesviruses, herpes simplex virus 1 (HSV-1) and human cytomegalovirus (HCMV)." (PMID 27935834, 2016). "cGAS deficiency and STING deficiency renders mice susceptible to HSE after peripheral infection in the eye, and correlates with impaired type I IFN expression in the CNS." (PMID 27830700, 2016). "find that SAMHD1, which blocks HIV-1 infection in myeloid cells, prevents innate sensing of infection via cGAS/STING." (PMID 27477283, 2016). "During infection with DNA viruses STING is activated downstream of cGAMP synthase (cGAS) to induce type I interferon." (PMID 26893169, 2016). "Not only can cGAS sense and respond to a variety of pathogens, it has also been postulated to provide a means of spreading intercellular signals of infection via its generation of the secondary messenger cGAMP." (PMID 25942676, 2015). "Moreover, it was recently shown that herpes simplex virus (HSV-1) induces the TLS pathway early during infection but the viral-encoded deubiquitinating enzyme, UL36USP, counters this to evade innate immune activation through cGAS." (PMID 41533576, 2026). "Infection of HSV-1 also leads to the SUMOylation of cGAS at K464, which enhances cGAS stability." (PMID 40470467, 2025). "Here, we evaluate the role of cGAS during BTV infection, showing that BTV induces cytosolic DNA accumulation, which could possibly be caused by mitochondrial stress during infection." (PMID 39836220, 2025). "Finally, an antagonist of the cGAS-STING pathway was able to ameliorate the decrease in electrical activity early post-infection." (PMID 41139159, 2025).
infection (continued). "Similarly, Yptb WT infection induced higher TNFα secretion in mouse peritoneal macrophages (PMs), which was attenuated in cGas−/− and Sting−/− PMs." (PMID 40365777, 2025). "By the time secondary infections occur, Rep has already accumulated in the cytosol (≥60 hpi) and could directly interact with cytosolic dsDNA to suppress cGAS activation." (PMID 40523029, 2025). "In addition, the Yptb WT infection‐elicited apoptosis was also attenuated in cGas−/− and Sting−/− PMs." (PMID 40365777, 2025). "Moreover, cGAS is rapidly activated upon viral dsDNA stimulation to initiate immune responses in the early stages of infection." (PMID 41196926, 2025). "Further, we show that mice deficient in the IFNα/β receptor subunit 1 (IFNAR1) or STING had higher bacterial burdens and increased renal colonization following infection in vivo suggesting that cGAS-STING-driven type I IFN is required for the host defense against L. interrogans." (PMID 40501870, 2025). "Interestingly, some RNA viruses have evolved mechanisms that antagonize the cGAS pathway during infections to avoid mtDNA sensing by cGAS." (PMID 39836220, 2025). "Furthermore, the HSV-1 virus, a DNA virus discussed earlier, induces mitochondrial damage and release of mitochondrial DNA (mtDNA) upon infection, triggering both the cGAS/STING/IRF3 and RIG-I-MAVS signaling pathways." (PMID 40016186, 2025). "BTV infection causes disruption of mitochondrial membrane and cytosolic DNA accumulation, which could potentially activate cGAS sensing of the infection." (PMID 39836220, 2025). "Interestingly, in macrophages, where cGAS is crucial for fighting infections, cGAS predominantly resides in the nucleus, despite the fact that these cells are not undergoing mitosis." (PMID 39623137, 2025). "Physiologically, this action may enable the cell to enhance IFN response when an intracellular infection, which activates cGAS, is concomitant with the presence of bacterial material outside the cell, activating TLR4." (PMID 40806167, 2025). "Our data showed that the cytoplasmic cGAMP levels in SFTSV-infected THP-1 cells were 1.7- to 5-fold higher than uninfected cells, and the production of cGAMP was partially inhibited with RU.521 existence, suggesting that the cGAS-STING signaling pathway can be activated after SFTSV infection." (PMID 40689679, 2025). "It is unlikely that cGAS activation is impacting viral entry into fibroblasts, as we still observe mCherry expression in the infected cells, as the viruses contain this fluorescent reporter allowing one to monitor infection." (PMID 40243337, 2025). "Early infection showed a subdued host response alongside elevated expression of Ct inclusion genes, while mid-infection revealed robust host immune activation, including upregulated interferon-stimulated genes and cGAS-STING and RLR pathway activation." (PMID 40599652, 2025). "Importantly, we conducted co-IP analysis using anti-4R-labeled agarose under the condition of ASFV infection, and found that MGF505-4R coprecipitated with cGAS during ASFV-WT infection in PAMs." (PMID 40618140, 2025). "To evaluate whether this degradation has a relevant biological role during infection or is a by-product of the infective process, we inhibited cGAS activity with the G140 inhibitor and measured viral replication." (PMID 39836220, 2025). "The nucleotidyltransferase cGAS has emerged as a key sensor of cytoplasmic DNA species that are derived from various sources, including infection with DNA viruses as well as with retroviruses, which generate DNA through reverse transcription of their RNA genomes." (PMID 41041557, 2025). "TREX1 therefore enhances infection by limiting innate immune activation by cGAS." (PMID 39804283, 2025). "Over the past years, the cGAS pathway is traditionally considered to be activated by binding to exogenous double-stranded DNA in cytoplasm and followed by initiating innate immune programs to protect against infection." (PMID 38766643, 2024).
infection (continued). "Specifically, the cyclic GMP‐AMP synthase (cGAS)‐ stimulator of interferon genes (STING) signaling axis has been shown to play an essential role in fighting infections by RNA viruses but also contributing to excessive inflammation associated with viral pathogenesis." (PMID 38509419, 2024). "Again, levels of infection were equivalent in WT and cGAS-/- cells." (PMID 38778414, 2024). "In this study, we reasoned that poxin-deficient viruses could be useful tools to understand how OPXV infections are sensed and the origin of the DNA PAMPs recognized by cGAS during infection." (PMID 39431915, 2024). "Though detection of endogenous swine cGAS is known to be difficult, a rapid decrease in the protein levels at early times after infection (3–6 h pi) could be detected in SK6 and WSL cells." (PMID 38509419, 2024). "On this basis, we found that −ssRNA SFTSV infection stimulated mtDNA release into the cytoplasm, and the depletion of mtDNA could block the activation of cGAS-mediated immune responses." (PMID 38712963, 2024). "An excessive DNA load due to infection or exposure to ultraviolet light exposure was shown to lead to the activation of cytosolic nucleic acid receptors, resulting in the activation of the cGAS-STING pathway and IFNα production." (PMID 38605949, 2024). "In addition, bacteriophages infecting bacteria where the cGAS/STING system evolved also develop mechanisms to evade their CBASS to establish infection." (PMID 38339107, 2024). "Furthermore, the use of cationic lipids to cause premature disruption of intracellular vesicular membranes during infection resulted in activation of the cGAS-STING pathway." (PMID 38675916, 2024). "Also, infection by West Nile virus, an ssRNA virus, leads to higher viral loads and mortality rates in cGAS knockout mice." (PMID 38831299, 2024). "A clear decrease in endogenous cGAS levels could be observed at 12 h after infection while STING levels remained more stable." (PMID 38509419, 2024). "Additionally, RT-qPCR showed that infection of SFTSV in cGAS−/− mice led to decreased transcription of inflammatory cytokines and type I IFN but increased SFTSV replication compared to the wild-type mice." (PMID 38712963, 2024). "Moreover, the NS1 protein of Influenza A virus has been shown to bind mitochondrial DNA (mtDNA) released to the cytoplasm during infection to evade the cGAS/STING-dependent antiviral immunity." (PMID 38509419, 2024). "CAD-dependent STING-activation may therefore expand the role of cGAS/STING in the recognition of infection considerably." (PMID 38849575, 2024). "Our observation that H37Rv-INH-R infection caused the highest ISG expression levels suggests a stronger induction of STAT1 as a result of cGAS-STING activation, rather than TLR2-MyD88 activation." (PMID 39597535, 2024). "Besides infection-triggered inflammation, the cGAS/STING pathway also promotes sterile inflammation in many other conditions involving cytosolic exposure of self-DNA, such as cell damage, senescence, diseases, and normal aging." (PMID 38177926, 2024). "Stimulator of interferon genes (STING) plays an important role in innate immunity and the inflammatory response by inducing interferons and other cytokines in response to the activation of the cyclic GMP-AMP synthase (cGAS) system by infection or tissue damage." (PMID 38786047, 2024). "Consequently, the cGAS-STING pathway has come to be recognized as a crucial pathway in the control of inflammation in relation to infection, cellular stress, and tissue damage." (PMID 39148120, 2024). "In addition to pathogen infection, the disruption of mitochondrial DNA integrity, replication, and repair can activate the cGAS-STING pathway." (PMID 37325622, 2023). "Considering that cGAS conjugation increased cGAMP production during infection, we examined whether Vs.4 might antagonize cGAS signalling by binding directly to cGAMP." (PMID 36848932, 2023).
infection (continued). "We hypothesized that BAF-mediated cGAS degradation may potentially be co-opted by the virus for immune evasion during primary infection to establish latency." (PMID 36746947, 2023). "Here, EV-A71 infection inhibited cGAS-STING-stimulated IFN-β promoter function." (PMID 36823147, 2023). "In addition, it has been shown that cytosolic mitochondrial DNA (mtDNA) plays important roles in cGAS-mediated antiviral immune responses after infection with RNA viruses, such as dengue virus and lymphocytic choriomeningitis virus (LCMV)." (PMID 36825026, 2023). "After using in vitro short hairpin RNA to interfere with cGAS and STING in human monocyte-macrophage lines, the type I interferons expression level significantly decreased following infection with Mycobacterium tuberculosis in the presence of restricted cGAS or STING expression." (PMID 37781360, 2023). "We examined the cGAS-STING signaling pathway of PAM infection with PRRSV by qRT-PCR." (PMID 37515271, 2023). "Furthermore, adult sting(−/−) fish had a high mortality rate and significantly downregulated cGAS–STING pathway-related genes during Edwardsiella piscicida (E. piscicida) infection." (PMID 36830693, 2023). "This could occur during infection by DNA viruses, bacteria and protozoa, where microbial DNA directly serves as pathogen-associated molecular pattern (PAMP) to trigger cGAS/STING activation." (PMID 37077526, 2023). "During pathogen infections, IL-1β secretion can upregulate antimicrobial immune responses by releasing mtDNA to activate the cGAS-STING signaling pathway, providing new insights into the mechanisms by which numerous cytokine-related pathways boost inflammatory responses." (PMID 37325622, 2023). "In addition, Ddx58 and cGAS, which encode factors for virus sensing, Stat1, Stat2, and IFN regulatory factor 7 and 9 mRNA levels were also induced at the initial stage of infection." (PMID 38125412, 2023). "Among them, cGAS can sense DNA viruses and trigger host immune responses upon infection." (PMID 36802406, 2023). "A basic research study, assessing the occurrence of VIS, found that human diploid fibroblast models exposed to high-titer retrovirus exhibited typical senescence and the activated cyclic GMP-AMP synthase-stimulator of interferon genes (cGAS-STING) pathway after the fifth day of infection." (PMID 37915066, 2023). "Theoretically, all nucleic acids, such as self-DNA and DNA–RNA hybrids, can be bound by cGAS; therefore, the cGAS–STING pathway is a major innate immune pathway triggered against infections by numerous diverse pathogens, such as DNA viruses, retroviruses, DNA-containing bacteria, and parasites." (PMID 37686127, 2023). "We surmise that in the presence of E5 during MVA infection, the virosomal progeny DNA might be protected from cGAS sensing." (PMID 37217469, 2023). "These nucleic acids mimic pathogen infection and are typical activators of cyclic GMP-AMP synthase (cGAS), a DNA sensor that triggers innate immune responses through the production of the second messenger cyclic GMP-AMP (cGAMP) and activation of the adapter protein STING5." (PMID 37783689, 2023). "As a DNA receptor, cGAS can recognize exogenous DNA, including infection related DNA from viruses and viruses or bacteria entering the cytoplasm, as well as self sourced DNA, including mitochondrial cytoplasmic DNA, DNA in cytoplasmic micronucleus and chromatin in nucleus." (PMID 37153576, 2023). "Moreover, ISG responses to iF17 infection were suppressed by treatment of NHDFs with a small molecule inhibitor of cGAS, even when added as late at 6 h.p.i." (PMID 38036506, 2023). "However, it remains to be determined about the SARS-CoV-2 antagonism of cGAS-mediated activation of IFN responses during infection." (PMID 37100798, 2023). "Similarly, NF-κB activation was observed after cGAS-STING stimulation yet was suppressed in the presence of EV-A71 infection." (PMID 36823147, 2023).
infection (continued). "How these posttranslational modifications of cGAS are regulated at different stages of infection and whether ubiquitination precede acetylation or vice versa may provide an approach to specifically target cGAS activity while preserving host-defense." (PMID 36139387, 2022). "Besides infection, numerous situations lead to the presence of aberrant host DNA in the cytoplasm leading to the activation of the cGAS–STING pathway, for instance in the context of mitochondrial stress, senescence and inflammation." (PMID 36359882, 2022). "Recently, it has been reported that attenuated ASFV NH/P68 strain, but not the virulent Armenia/07 strain, activates the cGAS-mediated innate immune signaling at very early phase of infection, indicating that cGAS is functional in sensing ASFV infection and is inhibited by virulent ASFV strains." (PMID 35089988, 2022). "We hypothesized that since ΔM062R infection of macrophages stimulated a cGAS-dependent IFN-I response, the infection will lead to similar results as dsDNA stimulated changes in the transcriptomic landscape." (PMID 36103568, 2022). "Caspase activity blocks cGAS/STING signaling during KSHV lytic infection." (PMID 36255240, 2022). "Thus, the investigation is underway or has been undertaken to determine strategies that allow selective regulation of cGAS-STING signaling activity in distinct infection settings." (PMID 35619707, 2022). "Coupled with this speculation, we also detected S. Typhimurium genes in the cytosolic fraction and showed physical interactions between cGAS and S. Typhimurium DNA in the context of infection." (PMID 35604097, 2022). "We have relied on our previous knowledge, as we have recently established that ASFV virulent strains efficiently block IFN-β production during PAM infection by preventing the activation of cGAS-STING pathway, whereas the natural attenuated strain NH/P68 does not." (PMID 36560402, 2022). "If indeed accelerated D2C replication induced DNA damage, then the type-I IFN expression upon D2C infection could be triggered via the cGAS/STING (cyclic GMA-AMP synthase/stimulator of IFN genes) pathway." (PMID 36514984, 2022). "In mammals, the cyclic GMP-AMP synthase (cGAS)-stimulator of interferon genes (STING) signaling pathway is responsible for detecting cytosolic DNA to trigger an effective innate immune response against pathogen infection." (PMID 35619707, 2022). "Interestingly, cGAS, initially known as a sensor of microbial DNA, was found playing an important role in limiting infections by RNA viruses." (PMID 36016430, 2022). "However, it was reported that CnpB inhibited the innate immune cytosolic surveillance such as cGAS-cGAMP pathway in macrophages, and autophagy is generally believed to help fight against infection." (PMID 35811674, 2022). "The cGAS-STING signaling is a key regulator of the interferon responses against pathogen infection." (PMID 36409895, 2022). "A549-ACE2 cells were depleted of cGAS using siRNA followed by infection with SARS-CoV-2." (PMID 35022513, 2022). "Double stranded DNA viruses target the cGAS pathway to facilitate infection." (PMID 35877778, 2022). "JEV can activate cGAS-STING signaling in the model of mouse embryonic fibroblasts infection." (PMID 36016430, 2022). "In addition to viral nucleic acids, infection of certain viruses can trigger mitostress, resulting in release of mitochondrial DNA that is sensed by cGAS and the subsequent innate antiviral response." (PMID 35089988, 2022). "cGAS-STING mainly recognized the cytoplasmic DNA produced by pathogen infection." (PMID 35837283, 2022). "To date, the cGAS–STING signalling pathway has emerged as a key mediator of inflammation in the settings of infection, cellular stress and tissue damage, and has recently emerged as a nodal player in immunity that is currently being explored as a potential therapeutic target." (PMID 36552020, 2022).